AKR1B1 (aldo-keto reductase family 1 member B)
Diseases named in the same sentence as AKR1B1 in open-access papers (continued):
Sharing a sentence is not in itself a finding about the gene and the disease.
depression (2 papers, 2023 to 2025). "Our results suggest that GenX exposure could reduce AKR1B1 expression, potentially promoting inflammation, impairing dopamine synthesis, and increasing susceptibility to depression." (PMID 41441267, 2025).
diabetic cardiomyopathy (2 papers, 2023). Diabetic cardiomyopathy is a disorder of the heart muscle in people with diabetes. "Indeed, the overexpression of AKR1B1 in transgenic mice has been shown to accelerate the onset of diabetic cataracts and exacerbate diabetic cardiomyopathy." (PMID 36839851, 2023).
Hepatic fibrosis (2 papers, 2021 to 2023). The presence of excessive fibrous connective tissue in the liver. "In addition, among all common targets for RGGs and liver fibrosis, ESR1, ESR2, AR, ACHE, CYP19A1, and AKR1B1 have a high degree of interaction with other targets and some active compounds." (PMID 35115923, 2021).
mood disorder (2 papers, 2025). A cognitive disorder a disturbance in which the person's mood is hypothesized to be the main underlying feature. "Evidence also links AKR1B1 to diabetic complications, elevated inflammatory cytokine levels, and mood disorders." (PMID 41441267, 2025). "Elevated AKR1B1 expression may exacerbate oxidative stress and contribute to neuronal damage and mood disorders." (PMID 40747300, 2025).
multiple myeloma (2 papers, 2020 to 2021). "Increased CDC25B, AKR1B1, and AKT3 expression was associated with poor multiple myeloma survival, indicating a detrimental effect of certain aging-associated gene patterns." (PMID 34831349, 2021).
non-small cell lung carcinoma (2 papers, 2022 to 2025). A group of at least three distinct histological types of lung cancer, including non-small cell squamous cell carcinoma, adenocarcinoma, and large cell carcinoma. "Schwab and colleagues reported that AKR1B1 knockdown inhibited EMT, proliferation and cancer stem cell markers on A549 non-small-cell lung cancer cells." (PMID 36552555, 2022).
varicocele (2 papers, 2020). A condition characterized by the dilated tortuous veins of the spermatic cord with a marked left-sided predominance. "All the DEPs overexpressed in the spermatozoa of men with bilateral varicocele compared to underexpressed proteins in unilateral varicocele were present in a high abundance except for AKR1B1 and PSMD13." (PMID 32365753, 2020).
adenoma (1 paper, 2016). A neoplasm arising from the epithelium. "Comparing adenoma + CRC with normal tissues, ADD2 and AKR1B1 have higher AUCs than SEPT9." (PMID 27493446, 2016).
Allergy (1 paper, 2016). An allergy is an immune response or reaction to substances that are usually not harmful. "In addition, the recent evidences on the involvement of AKR1B1 in allergy grant its study in association with these processes." (PMID 27540362, 2016). "Recent studies using pharmacological or genetic depletion establish a positive role for AKR1B1 in allergy." (PMID 27540362, 2016). "The mechanisms linking AKR1B1 with allergy are not fully understood." (PMID 27540362, 2016). "Interestingly, lodoxamide tromethamine, and several anti-allergy drugs, inhibit AKR1B1, providing additional possibilities of interaction with the hypersensitivity response." (PMID 27540362, 2016).
Cerebral ischemia (1 paper, 2023). Restriction of arterial blood supply to the brain associated with insufficient oxygenation to support the metabolic requirements of the tissue. "ROS formed after cerebral ischemia can activate the polyol pathway enzyme aldose reductase (AR; also known as AKR1B1) by modifying its cysteine residues to sulfenic acids." (PMID 36940077, 2023).
Cognitive impairment (1 paper, 2026). Abnormal cognition is characterized by deficits in thinking, reasoning, or remembering. "In vivo studies revealed that kaempferol improved cognitive impairments, reduced deposition of Aβ and p-Tau, and alleviated neuronal ferroptosis in the hippocampal tissues of an AD mouse model in a dose-dependent manner, effects that were diminished by inhibiting AKR1B1 expression." (PMID 42062795, 2026).
colitis (1 paper, 2025). Inflammation of the colon. "We and others have also reported the activation of inflammatory signaling in AKR1B1 overexpressing CRC cell lines and tumors as well as in mouse models of colitis with a high expression of AKR1B1." (PMID 40396420, 2025). "Other studies have shown that AKR1B1 may play a key role in the progression of colitis to CRC, further highlighting a role of AKR1B1 in inflammation." (PMID 40396420, 2025).
colorectal adenocarcinoma (1 paper, 2025). The most common type of colorectal carcinoma. "The data showed a clear colocalization of CD163 and AKR1B1 in macrophages both localized in the subepithelial portion of lamina propria in nonneoplastic colon mucosae and tumor stroma of colorectal adenocarcinoma." (PMID 40396420, 2025).
Colorectal Tumor (1 paper, 2025). "Previously, we have shown that high AKR1B1 mRNA expression in bulk colorectal tumor specimens was associated with worse prognosis, which could be validated using publicly available transcriptome data from multiple datasets." (PMID 40396420, 2025). "We assessed AKR1B1 expression in colorectal tumors utilizing publicly available transcriptomic data from CRC tumors." (PMID 40396420, 2025). "AKR1B1 was expressed in both the epithelial and stromal components of colorectal tumors, with higher expression observed in the stroma." (PMID 40396420, 2025).
gastric tumor (1 paper, 2023). "Compared with benign tissues, the CTLA4 and ENTPD2 were highly expressed in gastric tumor tissues, while the AKR1B1, CLDN6, EMB, GPR15 and VWF were highly expressed." (PMID 37066015, 2023).
inflammatory bone diseases (1 paper, 2025). "The pivotal role of AKR1B1 in naringenin’s mechanism highlights its potential as a therapeutic target for inflammatory bone diseases." (PMID 41173929, 2025).
kidney tumors (1 paper, 2015). "In fact, we found that taurine and sorbitol synthesis genes, CSAD and AKR1B1 respectively, are upregulated in many kidney tumors." (PMID 26439621, 2015).
leukemia (1 paper, 2024). A malignant (clonal) hematologic disorder, involving hematopoietic stem cells and characterized by the presence of primitive or atypical myeloid or lymphoid cells in the bone marrow and the blood. "Overexpression of AKR1B1 in leukemias was associated with TCF3-PBX1 gene fusion and rearrangements of the MLL gene located on chromosome 11q23." (PMID 39055885, 2024). "Analysis of the Oncomine database revealed significantly elevated expression of AKR1B1 in leukemias, lymphomas, and melanomas." (PMID 39055885, 2024).
metastatic tumours (1 paper, 2023). "The in-house primary and metastatic tumours showed an upregulated (not significant) expression pattern of AKRIBI expression in metastatic compared to primary tumours, which was consistent with AKR1B1 staining in the two matched primary and metastatic tumours." (PMID 37174052, 2023).
monocytic leukaemia (1 paper, 2020). "Besides, induction of NRF2 could silence human monocytic leukaemia cell line U937 and cause an increase in AKR1B1 expression suggesting that NRF2 may regulate AKR1B1 expression in peripheral blood cells." (PMID 32633024, 2020).
myocardial ischemia (1 paper, 2017). A disorder of cardiac function caused by insufficient blood flow to the muscle tissue of the heart. "Aldose reductase (AR: human, AKR1B1; mouse, AKR1B3), the first enzyme in the polyol pathway, plays a key role in mediating myocardial ischemia/reperfusion (I/R) injury." (PMID 29190815, 2017).
non-proliferative diabetic retinopathy (1 paper, 2025). Early stage diabetic retinopathy, characterized by the absence of neovascularisation of the retina. "Stratification analyses on proliferative diabetic retinopathy (PDR) and non-proliferative diabetic retinopathy (NPDR) were also conducted for seven genetic variants: Ins/Del variant at ACE gene; SNP rs759853 at AKR1B1 gene; SNPs rs1570360, rs2010963, rs3025039, rs699947, and rs833061 at VEGF gene." (PMID 40116328, 2025).
oral cancer (1 paper, 2022). "Our results show concordance with previous studies: gedunin, a limonoid compound, revealed the inhibition of AKR1B1 and its downstream (AKT, ERK and NF- κB), ROS generation and hypoxia-induced cell migration on SCC131 oral cancer cells." (PMID 36552555, 2022).
Osteopenia (1 paper, 2025). Osteopenia is a term to define bone density that is not normal but also not as low as osteoporosis. "Our work extends this paradigm to bone metabolism, proposing that AKR1B1 inhibition could mitigate inflammation-driven osteopenia." (PMID 41173929, 2025).
ovarian tumor (1 paper, 2022). "An enhanced expression of EMT and metabolism regulators including G6PD and AKR1B1 and TGFβ1 observed in vitro in carboplatin resistant cell line was confirmed in platinum resistant and relapsed human ovarian tumor samples, compared to chemo naïve human tumors." (PMID 36463238, 2022).
prediabetes (1 paper, 2022). "The concentration of AKR1B1, NOX1, MDA, SOD and GPx was measured between the NDP and PD group at the end of the prediabetes induction period." (PMID 35918636, 2022).
rectal tumor (1 paper, 2025). "When AKR1B1 expression was quantified in paired rectal tumor and adjacent normal tissues obtained from Serbian patients, its expression was significantly higher in tumors (p: 0.002), suggesting higher expression of AKR1B1 in tumor‐associated stroma and/or transformed epithelial cells." (PMID 40396420, 2025).
schizophrenia (1 paper, 2012). A major psychotic disorder characterized by abnormalities in the perception or expression of reality. "Besides categories related to hematological function, the Tan schizophrenia module was also enriched for the Neurological Disease category (CCL5, PRKCQ, PTAFR, AKR1B1, CD247, IL10RA and KHSRP)." (PMID 22761806, 2012).
signet ring carcinomas (1 paper, 2025). "We noted cases that lacked overall AKR1B1 staining, lacked staining in stroma, as well as weak staining in mucinous and signet ring carcinomas (data not shown)." (PMID 40396420, 2025).
urothelial carcinoma (1 paper, 2023). A malignant neoplasm derived from the transitional epithelium of the urinary tract (urinary bladder, ureter, urethra, or renal pelvis). "Among genes recorded in “Pathology” section in THPA, staining intensities of AKR1B1, TCHH, AKAP12, and IGF2 are distinctly higher in tissues from urothelial carcinoma than in normal bladder." (PMID 36512456, 2023).
cancer (80 papers, 2002 to 2025). A tumor composed of atypical neoplastic, often pleomorphic cells that invade other tissues. "AKR1B1, a promising diagnostic biomarker and its inhibition has been shown to enhance the sensitivity of tumor cells to anti-cancer drugs." (PMID 40088196, 2025). "We observed that the loss of AKR1B1 dramatically restrained the incorporation of 5-ethynyl-2’-deoxyur-idine (EdU) into the nucleus of the cancer cells with impaired endogenous fructose metabolism." (PMID 39406918, 2024). "Aldo–keto reductase family 1 member B1 (AKR1B1) is closely implicated in cancer development and progression through various mechanisms, including EMT, ERK1/2, Ras, and PI3K-AKT signaling pathways." (PMID 39749345, 2024). "Overexpression of AKR1B10 was seen in cancers of the lungs and liver associated with a less aggressive clinical course, whereas AKR1B1 was more widely overexpressed in several cancers and associated with shortened patient survival." (PMID 39055885, 2024). "AKR1B1 is implicated in the progression of multiple type of cancers, but the underlying mechanisms remains elusive, particularly in GC." (PMID 36397644, 2023). "AKR1B1, an enzyme involved in the reduction of the aldehydic group of lipid peroxidation end-product, has been implicated in many cancers and has been linked to processes like inflammation, EMT and cancer." (PMID 37174052, 2023). "On the other hand, lower expression of AKR1B1, associated with 2‐Deoxyglucose (2DG) that is an anti‐cancer drug and a substrate for AKR1B1, causes more drug resistance in tumour cells." (PMID 32633024, 2020). "AKR1B1 has been reported overexpressed in cancer and is associated with inflammatory mediators including nuclear factor kappa-light-chain enhancer of activated B cells (NFκB), as well as cell cycle mediators such as cyclin-dependent kinases (CDKs), and survival proteins." (PMID 40088196, 2025). "AKR1B1 overexpression causes tumor progression via several signaling pathways in cancer cells." (PMID 40361399, 2025). "This study found that high glucose levels enhance AKR1B1 expression and may explain the elevated cancer risk in diabetic patients." (PMID 39406918, 2024). "Recent evidence has implicated AKR1B1 in cancer; however, the mechanisms underlying its pro-oncogenic function remain largely unknown." (PMID 37780210, 2023). "In many cancers, such as breast, AKR1B1 has been known to be associated with EMT." (PMID 37174052, 2023). "In addition, AKR1B1 has been implicated in the development of several human cancers and resistance to certain anticancer drugs." (PMID 37185746, 2023). "The results of the current study are very promising therefore suggested that both compounds can be used in future for the synthesis of more potential inhibitors of the selected targets, for the treatment of respective cancers caused due to over-expression of AKR1B1 and AKR1B10." (PMID 36301939, 2022). "AKR1B1 could also be considered as a potential cancer diagnostic biomarker since its promoter has shown high levels of methylation." (PMID 32633024, 2020). "The aldo-keto reductase family 1 member B1 (AKR1B1) plays a key role in cancer progression by competing with histone deacetylase 3 to bind to the deacetylase activation domain (DAD) of the nuclear receptor corepressor SMRT." (PMID 40309007, 2025). "Nevertheless, renewed interest is emerging, as the role of AKR1B1 in cancer, fibrosis, and oxidative stress becomes clearer, inspiring the development of next-generation, tissue-specific inhibitors." (PMID 41154825, 2025). "AKR1B1 is considered a pharmacological target due to its role on diabetic inflammatory pathologies, overexpression in various types of cancer, and its role in promoting epithelial-mesenchymal transition." (PMID 40309007, 2025).
cancer (continued). "For instance, AKR1B1, frequently overexpressed in several cancers, plays diverse roles in cell cycle regulation and epithelial-mesenchymal transition (EMT)." (PMID 40001235, 2025). "We then evaluated the impact of AKR1B1-mediated glucose-derived fructose production on the proliferation of cancer cells." (PMID 39406918, 2024). "Further clarification is needed to understand the reasons behind cancer cells’ induction of AKR1B1-mediated fructose synthesis from glucose as a substrate." (PMID 39406918, 2024). "Inhibiting the endogenous production of fructose through AKR1B1 deletion dramatically suppressed glycolysis, resulting in reduced cancer cell migration, inhibited growth, and the induction of apoptosis and cell cycle arrest." (PMID 39406918, 2024). "Our findings highlight the crucial role of endogenous fructose in cancer cell malignancy and support the need for further investigation into AKR1B1 as a potential cancer therapeutic target." (PMID 39406918, 2024). "These in vitro results demonstrated that glucose-derived intracellular fructose production and metabolism through the AKR1B1-mediated polyol pathway was critical for the neoplastic phenotypes of cancer cells." (PMID 39406918, 2024). "In this study, we demonstrate that cancer cells can convert glucose into fructose through a process called the AKR1B1-mediated polyol pathway." (PMID 39406918, 2024). "Flow cytometric analysis showed that blocking the conversion of glucose to fructose in cancer cells by knocking out the gene AKR1B1 significantly increased cell apoptosis and caused cell cycle arrest at the S phase." (PMID 39406918, 2024). "Conversely, the acceleration of endogenous fructose through AKR1B1 overexpression has been shown to significantly enhance cancer cell proliferation and migration with increased S cell cycle progression." (PMID 39406918, 2024). "We identified that the AKR1B1-mediated polyol pathway, which is highly active in cancer cells, is a key mechanism for producing fructose from glucose." (PMID 39406918, 2024). "Overall, these data demonstrated that endogenous fructose production and metabolism from glucose through the AKR1B1-mediated polyol pathway was necessary for cancer cell growth in vivo." (PMID 39406918, 2024). "As the first step enzyme, we therefore investigated the clinical significance of AKR1B1 expression in pan-cancer from human TCGA database." (PMID 39406918, 2024). "Analysis of the Oncomine cancer gene expression database revealed wide variations in the expression of AKR1B1 and AKR1B10 in different cancer types." (PMID 39055885, 2024). "We then conducted the following assays to ascertain the mechanism by which AKR1B1-mediated polyol pathway promoted cancer cell migration." (PMID 39406918, 2024). "Deletion of AKR1B1 significantly inhibited cancer cell migration, as demonstrated by both wound healing and transwell assays." (PMID 39406918, 2024). "Under high glucose (25 mM) concentrations, the cancer cells significantly increased their AKR1B1 expression levels compared to those grown in low glucose (2.5 mM)." (PMID 39406918, 2024). "What’s more, overall survival (OS), progression-free interval (PFI) and disease specific survival (DSS) curves of AKR1B1 in pan-cancer from TCGA database showed that tumor patients with high expression of AKR1B1 had worse prognosis." (PMID 39406918, 2024). "We further investigated the impact of AKR1B1-mediated fructose production on the migration capacity of cancer cells." (PMID 39406918, 2024). "Epalrestat enhances the chemosensitivity of cancer cells to doxorubicin by inhibiting the activity of AKR1B1 and/or AKR1B10 as well as by preventing epithelial-mesenchymal transition." (PMID 39055885, 2024). "Trans-(±)-kusunokinin ((±)KU), a synthetic antiproliferative agent that inhibits the growth of several malignant tumor cells both in vitro and in vivo, was shown to be a selective inhibitor of AKR1B1." (PMID 39055885, 2024).